ACMSD (aminocarboxymuconate semialdehyde decarboxylase)
Description:
Converts alpha-amino-beta-carboxymuconate-epsilon-semialdehyde (ACMS) to alpha-aminomuconate semialdehyde (AMS). ACMS can be converted non-enzymatically to quinolinate (QA), a key precursor of NAD, and a potent endogenous excitotoxin of neuronal cells which is implicated in the pathogenesis of various neurodegenerative disorders. In the presence of ACMSD, ACMS is converted to AMS, a benign catabolite. ACMSD ultimately controls the metabolic fate of tryptophan catabolism along the kynurenine pathway.
Tractability: Small molecule: a structure with a bound ligand is known; a high-quality ligand is known; it has a binding pocket of medium quality. PROTAC: its protein half-life has been measured; a small molecule that binds it is known.
Target class: Enzyme; Lyase
Chemical probes: TES-1025
Gene: Protein-coding gene on chromosome 2 (134,838,312 to 134,902,906, forward strand). Ensembl gene ENSG00000153086.
Subcellular location (Human Protein Atlas): Cytosol
Pathways (Reactome):
Metabolism: Tryptophan catabolism
Gene Ontology:
Molecular function: aminocarboxymuconate-semialdehyde decarboxylase activity; protein binding; zinc ion binding; carboxy-lyase activity; hydrolase activity
Biological process: negative regulation of quinolinate biosynthetic process; L-tryptophan catabolic process; picolinic acid biosynthetic process; regulation of 'de novo' NAD biosynthetic process from L-tryptophan; secondary metabolic process
Cellular component: cytosol; cytoplasm
Genetic constraint (gnomAD): Loss-of-function variants: 29 observed, 37.18 expected, observed/expected ratio (o/e) 0.78, 90% interval 0.58 to 1.06. The upper end of that interval is the gene's LOEUF score, 1.06, which puts it in group 4 of 6, group 1 being the genes least tolerant of losing a copy. Missense variants: 350 observed, 356.69 expected, observed/expected ratio (o/e) 0.98, 90% interval 0.9 to 1.07. Synonymous variants: 113 observed, 126.72 expected, observed/expected ratio (o/e) 0.89, 90% interval 0.76 to 1.04.
Homologues: Orthologues: chimpanzee ACMSD (99% identical), macaque ACMSD (94% identical), dog ACMSD (91% identical), guinea pig ACMSD (90% identical), mouse Acmsd (87% identical), rat Acmsd (86% identical), zebrafish acmsd (81% identical), pig ACMSD (80% identical), tropical clawed frog acmsd (75% identical), Caenorhabditis elegans acsd-1 (51% identical).
Diseases named in the same sentence as ACMSD in open-access papers:
ACMSD is named in the same sentence as 23 diseases in open-access papers, as found by Europe PMC text mining. Sharing a sentence is not in itself a finding about the gene and the disease. The quoted sentences say what the papers report.
Parkinson disease (5 papers, 2012 to 2025). A progressive degenerative disorder of the central nervous system characterized by loss of dopamine producing neurons in the substantia nigra and the presence of Lewy bodies in the substantia nigra and locus coeruleus. "A disease-segregating mutation in the ACMSD gene (pTrp26Stop) has been reported in a Spanish family with cortical myoclonus, epilepsy, and parkinsonism." (PMID 40346140, 2025).
glioma (2 papers, 2014 to 2026). A benign or malignant brain and spinal cord tumor that arises from glial cells (astrocytes, oligodendrocytes, ependymal cells). "Downregulation of ACMSD expression, commonly observed in gliomas, leads to a significant shift in metabolic flux toward QUIN and nicotinamide adenine dinucleotide (NAD+) synthesis pathways." (PMID 41602107, 2026). "Down-regulation of ACMSD in stimulated glioma cells compared to unstimulated glioma cells in the present study may further direct KP metabolism away from the metabolite PIC and towards QUIN and NAD+ production under conditions of inflammatory stress in the tumor microenvironment." (PMID 25415278, 2014).
Stroke (2 papers, 2021 to 2025). Sudden impairment of blood flow to a part of the brain due to occlusion or rupture of an artery to the brain. "In accord with changes of metabolite levels, activities of KP enzymes differed as well: IDO1, KMO, 3-hydroxyanthranilate 3,4-dioxygenase (3-HAO) and the composed 3-HAO and aminocarboxymuconate semialdehyde decarboxylase (ACMSD) activity was higher in stroke patients compared to controls." (PMID 34680558, 2021). "ACMSD, a pivotal regulator of the kynurenine pathway, offers a novel therapeutic strategy to combat NAD+ depletion, a core metabolic defect in stroke driving mitochondrial dysfunction and cognitive decline." (PMID 41184254, 2025).
acute kidney injury (1 paper, 2022). Sudden and sustained deterioration of the kidney function characterized by decreased glomerular filtration rate, increased serum creatinine or oliguria. "In vivo efficacy data obtained with TES-1025 in preclinical murine models of liver and kidney diseases suggested ACMSD as a promising novel therapeutic target to improve health in pathological settings such as that of acute kidney injury (AKI)." (PMID 35463964, 2022).
Anxiety (1 paper, 2025). Intense feelings of nervousness, tension, or panic often arise in response to interpersonal stresses. "While ACMSD knockdown improves cognitive recovery in aged mice, therapeutic translation requires careful calibration: excessive pathway activation risks accumulating neurotoxic quinolinic acid, potentially exacerbating anxiety symptoms." (PMID 41184254, 2025).
bowel cancer (1 paper, 2022). "However, research on proteasome 20S subunit beta 2 (PSMB2) and aminocarboxymuconate semi-aldehyde decarboxylase (ACMSD) are waiting to be explored in bowel cancer." (PMID 36035152, 2022).
brain tumors (1 paper, 2022). "Contrastingly, the expression of the KP enzymes that lead to NAD+ synthesis, KYNU, HAAO, ACMSD, and QPRT were significantly increased in brain tumors compared to the brain cortex." (PMID 36355137, 2022).
kidney damage (1 paper, 2026). "Herein, we demonstrated that ACMSD promotes AKI by stimulating TCA cycle and exacerbating ferroptosis process, its knockdown in vitro blocks this process and reverses kidney damage." (PMID 41356196, 2026).
liver disease (1 paper, 2025). "In this study, we aimed to investigate the therapeutic implications of ACMSD inhibition in the treatment of metabolic dysfunction-associated steatotic liver disease/steatohepatitis (MASLD/MASH)." (PMID 39181211, 2025).
pellagra (1 paper, 2018). "The need to prevent the accumulation of neurotoxic intermediates such as quinolinic acid likely caused evolutionary pressures favoring high ACMSD activity in humans, which in turn increases pellagra susceptibility." (PMID 30380424, 2018). "We generated a transgenic mouse model with inducible human (h)ACMSD overexpression (acquired niacin deficiency, or ANDY, mouse) to test the hypothesis that elevated ACMSD activity renders rodents niacin dependent, which should result in NAD+ deficiency on a niacin-free diet." (PMID 30380424, 2018).
tumor (5 papers, 2014 to 2026). "Intriguingly, ACMSD remained unchanged or down-regulated in these subtypes suggesting a KP pathway shift towards quinolinic acid and energy production (thereby facilitating tumour progression) and away from production of the tumour suppressive metabolite picolinic acid." (PMID 26646699, 2016). "This metabolic imbalance results from upregulated activity of tumor-promoting enzymes (IDO1, TDO2, KMO, KYNU) alongside downregulated protective enzymes(KATs, ACMSD)." (PMID 41602107, 2026). "The strategy of restoring or expressing ACMSD function can effectively reduce the cyclization of ACMS to QUIN, reduce the production of neurotoxic metabolites, and inhibit the energy supply of the tumor." (PMID 41602107, 2026). "In particular, GGACT, LXN, THY1, SYNPO2, ACMSD and COLEC11 showed no survival or recurrence associations from the tumor data, suggesting these as unique biomarkers from NAT." (PMID 37575948, 2023). "In contrast, both the low-metastatic risk luminal A and B subtypes showed no changes in KP apart from elevated ACMSD mRNA, which as discussed, could lead to higher concentrations of picolinic acid and a more tumour suppressive KP profile." (PMID 26646699, 2016). "Using our dataset and another high-quality dataset, we identified proteins that showed clinical prognosis and recurrence associations, of which GGACT, LXN, THY1, SYNPO2, ACMSD and COLEC11 were unique biomarkers identified from NAT that could not be revealed using tumor-based analysis." (PMID 37575948, 2023).
cancer (1 paper, 2022). A tumor composed of atypical neoplastic, often pleomorphic cells that invade other tissues. "Similarly, the down regulation of 3-HAAO in 19/28 cancers is unlikely to result in impaired formation of QA, as the Km of the enzyme for 3-HAA is even much lower (2–3.6 μM) and especially if ACMSD is expressed in only three cancers (in association with expression of FAMID and TDO2)." (PMID 36286592, 2022).
neurodegenerative disease (1 paper, 2018). A disorder of the central nervous system characterized by gradual and progressive loss of neural tissue and neurologic function. "This study shows that ACMSD is a key regulator of mammalian dietary niacin requirements and NAD+ metabolism and that the ANDY mouse represents a versatile platform for investigating pathologies linked to low NAD+ levels in aging and neurodegenerative diseases." (PMID 30380424, 2018).
renal diseases (1 paper, 2022). "The results provide new structural information about the mechanism of inhibition exerted by a novel class of compounds on the ACMSD enzyme, a novel therapeutic target for liver and kidney diseases." (PMID 35463964, 2022).
ACMSD also shares sentences with these, for which no sentence is quoted: AIDS (1 paper); breast carcinoma (1); cognitive decline (1); diabetes (1); epilepsy (1); metabolic dysfunction-associated steatotic liver disease (1); Obesity (1); Parkinsonism (1); type 2 diabetes (1).